DUSP9 (dual specificity phosphatase 9)
Diseases named in the same sentence as DUSP9 in open-access papers (continued):
Sharing a sentence is not in itself a finding about the gene and the disease.
cancer (15 papers, 2010 to 2025). A tumor composed of atypical neoplastic, often pleomorphic cells that invade other tissues. "We then performed MTT assays and clonogenic cell survival assays to further confirm whether loss of NF1 and DUSP9 causes lenvatinib resistance in cancer cells." (PMID 34795217, 2021). "For this reason, DUSP9 is considered an ambiguous phosphatase in the context of cancer onset and development." (PMID 40943262, 2025). "We observed that manipulation of DUSP9 expression led to corresponding changes in the expression of core cancer stemness genes, including SOX2, NANOG and OCT4." (PMID 41383134, 2025). "In line with the antitumoural role of DUSP9 in this cancer, another study reported that DUSP9 was significantly downregulated in CRC tissues compared with peritumoural ones." (PMID 40943262, 2025). "In this section, we summarize the main data gathered from the literature on the role of DUSP9 in cancer." (PMID 34768967, 2021). "Together, these data suggest that DUSP9 contributes to cancer stemness and drug resistance and thus positively influences the growth and progression of TNBCs." (PMID 34768967, 2021). "Given the central role of DUSP9 in cancer and metabolic diseases, some groups have attempted to identify potent molecules specifically targeting it." (PMID 34768967, 2021). "In order to further explore the reason for the decrease of DUSP9 in CRC, we used MethHC (the human pan-cancer methylation database) to predict the methylation status in DUSP9 gene promoter." (PMID 33072575, 2020). "Consistent with previous reports of other cancers, low-expression of DUSP-9 indicated poor prognosis for patients with ccRCC." (PMID 21943117, 2011). "In addition, the dual-specificity protein phosphatase protein family (DUSP10/MKP-5, DUSP9/ MKP-4) shows antagonistic effects in cancer and fibrosis." (PMID 38730387, 2024). "DUSP9 is central in tumorigenesis and is involved in many adult and pediatric cancers." (PMID 34768967, 2021). "Recently, increasing attention has been paid on the role of DUSP9 in a variety of cancers." (PMID 33072575, 2020). "In addition, other well-known cancer-associated genes (including VEGFA, DUSP9 and ERBB4) were also selectively validated as exhibiting consistently disrupted expression patterns in most of the ccRCC samples profiled." (PMID 21253009, 2010). "Additionally, DUSP9 expression escalated with individual cancer stage in the early phases." (PMID 40861803, 2025). "Finally, DUSP9 can be regulated by microRNAs (miRNAs), which are small non-coding RNAs that act as post-transcriptional regulators and which are often deregulated in pathological conditions and cancers." (PMID 34768967, 2021). "As for the DNA methylation, the cancers and the corresponding genes with hypermethylation were as follows: BRCA: VWF and ITGB3; COAD: QKI, DUSP9, and CNKSR2; KIRC: CNKSR1; PRAD: VWF, LMNA, and ITGB3; UCEC: ITGB3 and APBBAIP." (PMID 38217548, 2024). "Therefore, hypermethylation of the CpG islands near the transcription initiation site of DUSP9 promoter could in part explain DUSP9 downregulation in CRC and other cancers." (PMID 34768967, 2021). "Although data from two conflicting reports do not suggest the pro-tumorigenic role of DUSP9 in TNBC, DUSP9 regulates the ERK pathway in TNBC and plays a role in chemotherapeutic resistance and cancer stemness of TNBC cells." (PMID 34768967, 2021).
metabolic disorders (2 papers, 2019 to 2021). "DUSP9 has a central role in sex differences, metabolic disorders and tumorigenesis." (PMID 34768967, 2021).
benign tumors (1 paper, 2011). "Loss of DUSP-9 was associated with SCC, and it independently induced SCCs relative to benign tumors in mouse skin." (PMID 21943117, 2011).
cardiac diseases (1 paper, 2021). "In absence of additional reports on the role of DUSP9 in heart pathologies, future studies are required to improve our understanding of the relationship between DUSP9 phosphatase and cardiac diseases." (PMID 34768967, 2021).
DUSP9 also shares sentences with these, for which no sentence is quoted: clear cell renal cell carcinoma (2 papers); alveolar soft part sarcoma (1); bladder urothelial carcinoma (1); breast invasive carcinoma (1); cervical squamous cell carcinoma (1); chronic myeloid leukemia (1); colon adenocarcinoma (1); colorectal adenoma (1); endocervical adenocarcinoma (1); Glucose intolerance (1); head and neck squamous cell carcinoma (1); head and neck tumors (1); heart failure (1); Hyperglycemia (1); infection (1); ischemia (1); leukemia (1); liver cirrhosis (1); liver diseases (1); liver fibrosis (1); lung adenocarcinoma (1); morbid obesity (1); nevus (1); pancreatic adenocarcinoma (1); prostate carcinoma (1); Sepsis (1); triple-negative breast carcinoma (1).